MDM4 (MDM4 regulator of p53)
Diseases named in the same sentence as MDM4 in open-access papers (continued):
Sharing a sentence is not in itself a finding about the gene and the disease.
tumor (continued). "Here, we present the first known case of an RB tumor with a segmental copy number gain peaking at MDM4, detected in AH at diagnosis and monitored using the AH longitudinally for therapeutic response." (PMID 40834326, 2025). "To improve the therapeutic potential of peptides that interfere with MDM4 binding to MDM2, we demonstrated the tumor‐suppressive activity of a short peptide (Pep3S), which is composed of the last five amino acids of the MDM4 protein." (PMID 40022459, 2025). "AH cfDNA analysis further revealed multiple SCNAs restricted to the tumor, including duplications in MDM4, ALK, CCND3, and BRAF, as well as deletions in TFRC, FGF3, FGF9, and BRCA2." (PMID 41465072, 2025). "Given the multi-functional nature of MDM4, the detailed mechanism and involved pathway of MDM4 in tumor needed further investigation." (PMID 38281029, 2024). "Patients with MDM2/MDM4 amplification were taken off immunotherapy in less than two months, and four showed a clearly accelerated rate of tumour growth compared to that before treatment." (PMID 39530091, 2024). "The impact of MDM4 on tumor development also depends on its alternative splicing, including the two most studied isoforms, MDM4-FL (full-length) and MDM4-SF (short form)." (PMID 38281029, 2024). "To explore the role of MDM4 in tumorigenesis, malignant progression and tumor lethality, we evaluated the genomic heterogeneity index, which is known to affect clinical outcomes such as TMB, HRD, LOH, MATH, MSI, and Neoantigens." (PMID 38281029, 2024). "Amplifications of MYC (four cases), MDM2 (two cases), MDM4 (two cases), and several other genes were identified with the Illumina TruSight Tumor 170 panel in a subset of tumors." (PMID 37891989, 2023). "We further evaluated the potential effects of MDM4 on tumour growth by using xenograft mouse model, which were injected with A549 cells or cells with MDM4 knockdown subcutaneously." (PMID 37817427, 2023).
tumor (continued). "In this in vivo treatment setting, the sustained KD of MDM4 as a single treatment slowed tumour growth and significantly improved survival for mouse recipients of both xenotransplanted lines." (PMID 36010941, 2022). "Our analysis revealed that PC patients with the highest levels of MDM4 expression in their primary PC tumours showed reduced survival probability as compared with those with lower MDM4 levels." (PMID 36010941, 2022). "USP2 was responsible for stabilizing many tumor-associated proteins, including FASN, mouse double minute 4 (MDM4)/MDMX and cyclin D1." (PMID 35307036, 2022). "Noteworthy, treatment of animals with fulvestrant rescues MDM4-mediated proapoptotic activity and increases tumor sensitivity to chemotherapy." (PMID 34307167, 2021). "Although tumours with gene amplification and overexpressing MDM2 and MDM4, the negative regulators of p5330,31, are obvious candidates for such therapy, other tumours should be targetable with this type of compound." (PMID 34711913, 2021). "They showed that ERα is a positive regulator of MDM4 oncogenic activity, and treatment of tumor cells with ER inhibitors (fulvestrant or OHT) reduces MDM4 protein levels." (PMID 34307167, 2021). "Induced skipping of exon 6 leading to decreased MDM4 abundance, thereby inhibiting tumor growth and enhancing sensitivity to MAPK-targeting therapeutics." (PMID 34769221, 2021). "At the necropsy, all mice injected with SK-OV-3 cells showed tumor nodules independently of MDM4 expression." (PMID 34052831, 2021). "SK-OV-3 cells were engineered to express human MDM4 or Empty Vector as control and the mCherry marker to visualize in vivo tumor nodules." (PMID 34052831, 2021). "Accordingly, MDM4 nuclear localization and intra-tumor estrogen availability correlate with decreased platinum sensitivity and apoptosis and predict poor disease-free survival in human HGSOC." (PMID 34307167, 2021). "Because the ratio of MDM4-FL to MDM4-S mRNA is correlated with the level of MDM4 protein in several tumor cell lines, this ratio is considered more useful for investigations of MDM4 expression in target tissues or cells." (PMID 34144037, 2021). "MDM4 inhibition also showed efficacy in a murine model of HB with significantly decreased tumor weight and increased apoptosis observed in the treatment group." (PMID 33536467, 2021).
tumor (continued). "Modulation of MDM4 expression in BC cell lines showed a positive correlation with cell migration and the number of circulating tumor cells compared to orthotopic tumors." (PMID 33007869, 2020). "For example, previous research revealed that MDM4 was significantly overexpressed in renal cancer and impeded the tumor progression." (PMID 33146951, 2020). "Compared to normal tissues, the level of MALAT1 was distinctly increased in 30 paired NSCLC tumor tissues, and the same result was observed in the mRNA and protein abundances of MDM4." (PMID 33146951, 2020). "On the molecular level, the analysis of the explanted tumor tissues revealed alterations in the expression of murine double minute 4 (MDM4) which has been described previously as direct target of miR-150." (PMID 33228711, 2020). "Amplifications of EGFR and gain of chromosomes 19 and 20 were strongly prevalent in RTK II, and PDGFRA, CDK4 and MDM2 or MDM4 amplifications were more frequent in RTK I tumours." (PMID 33339831, 2020). "In vitro studies on primary cells and tumor cell lines gave insight into the molecular mechanism by demonstrating that ERα alters the subcellular localization of both mouse and human MDM4, increasing its nuclear fraction and subsequent degradation." (PMID 31547268, 2019). "Tumor cells were classified as presenting only nuclear or nuclear and cytoplasmic MDM4 signal, and a final score (based on the intensity and the percentage of positive cells) was assigned to each tumor, for each pattern of MDM4 expression." (PMID 31547268, 2019). "SNP34091 is assumed to alter MDM4 levels by creating a putative target site for hsa-miR-191, a microRNA highly expressed in tumor tissues." (PMID 31547268, 2019). "Sequencing identified germline and tumor amplified, expressed, high-impact druggable variants in two genes (ABL1, NOTCH1) and expressed, medium impact variants in three additional genes (MDM4, PAK4, MAP4K5)." (PMID 31208434, 2019). "The presence of the transgene significantly decreased the latency of tumor formation in Mdm4Tg15 mice compared to littermate control animals (WT), indicating that Mdm4 oncogenic properties prevail over its pro-apoptotic activities in this model." (PMID 31547268, 2019).
tumor (continued). "Additionally, the association of tumor HPV16 status with combined MDM4 risk genotypes in SCCOP was more evident among ever-drinkers in the current study, implying HPV16 could interact with alcohol and smoking, even though non-drinkers more likely had HPV-positive tumors than ever-drinkers." (PMID 29156829, 2017). "Recent studies indicate that MDM4-S transcripts regulate the abundance of MDM4 protein and that the MDM4-S/MDM4 ratio correlates with tumor aggressiveness." (PMID 28460439, 2017). "In the present study, a significant association between the three MDM4 polymorphisms and HPV16 tumor status in patients with SCCOP were found; and such associations were more pronounced among some subgroups." (PMID 29156829, 2017). "Overall, these data identify MDM4 as a nutrient-sensor able to inhibit mTORC1 and highlight its metabolism-related tumor-suppressing function." (PMID 28270148, 2017). "Accordingly, it has recently been shown that antisense oligonucleotide-mediated skipping of exon 6 decreased MDM4 abundance and reduced the growth of various human tumor cells." (PMID 28230750, 2017). "Three polymorphisms in MDM4 were genotyped from blood genomic DNA samples and HPV16 status in tumor specimens was examined." (PMID 29156829, 2017). "Amplifications of the four regions at 1q were divided over two tumors, one tumor (T58) with similar copy number for all four regions indicating co-amplification and one tumor (T21) with only 1q32.1 amplification including MDM4 and 26 other genes." (PMID 27126562, 2016). "Other alterations such as amplifications of PDGFRA, MDM2 and MDM4 were also identified as important events occurring at different steps of tumor expansion depending on the patient." (PMID 25940437, 2015). "Although MDM4 expression was very low to undetectable (<10% MDM4 positive cells) in 24/36 (66.7%) of tumour samples, strong positive staining was observed in 12/36 (33.3%) cases." (PMID 26095524, 2015).
tumor (continued). "We found that 3/4 of the samples with discordant SNP genotyping between germline and tumor had copy number gain of MDM4 in the tumor." (PMID 22916154, 2012). "The majority of MDM2 SNP309 (36/41 (88%)) and MDM4 SNP7 (39/43 (91%)) genotypes were identical between the tumor and germline samples." (PMID 22916154, 2012). "In 2006, along the analysis of MDM2 alternative transcripts induced by UV irradiation in some human tumor cell lines, Lozano’s group found out two alternative transcripts of MDM4, called XALT1 and XALT2." (PMID 19721810, 2009). "This review summarizes all the different MDM4 splicing forms thus far described and their role in the regulation of the wild type protein function in normal and tumor cells." (PMID 19721810, 2009). "The first observation derived from Jochemsen’s group, which reported the presence by immunoblot (WB) analysis of at least 5 shorter MDM4 forms in a panel of 31 human tumor cell lines." (PMID 19721810, 2009). "Additionally, two cases (RB36 and RB37) showed CNA in ABL2 and MDM4 genes, with the latter alteration found only in the tumor sample." (PMID 40332023, 2025). "While MDM4 amplification has been reported in RB tumor tissue, its clinical relevance in treatment response remains unclear." (PMID 40834326, 2025). "As expected, the expression of MDM4 in tumor samples was higher than that in paired normal tissues." (PMID 38281029, 2024). "On the whole, the pro-tumor function of MDM4 is complicated and multifaceted." (PMID 38281029, 2024). "Furthermore, we explored the anti-tumor efficacy of small molecule MDM4 inhibitor in vitro experiments." (PMID 38281029, 2024). "MDM4 isoforms are also closely related to tumor progression." (PMID 38281029, 2024). "Moreover, in this group, overexpression was found in several tumor oncogenic genes (such as CCND1, MDM2, MDM4, and DNMT3A), which positively associated with hyperprogression, which led to ICB-related high progression of the disease." (PMID 35909893, 2022).